ILF2 (interleukin enhancer binding factor 2)
Diseases named in the same sentence as ILF2 in open-access papers (continued):
Sharing a sentence is not in itself a finding about the gene and the disease.
cancer (29 papers, 2012 to 2025). A tumor composed of atypical neoplastic, often pleomorphic cells that invade other tissues. "The current investigation identified that ILF2 displays enhanced expression in a variety of cancers and that elevated expression of ILF2 is implicated in poor clinical outcomes." (PMID 35333683, 2022). "Furthermore, we discuss the potential of ILF2 as a prognostic biomarker, diagnostic marker, and therapeutic target in cancer treatment." (PMID 39735599, 2024). "High ILF2 expression is associated with poor prognosis in patients with malignant tumors." (PMID 39735599, 2024). "Therefore, elucidating the molecular mechanisms underlying ILF2 ability to induce cancer cell proliferation and whether this is mediated by ILF2–ILF3 interactions in HCC pathogenesis, requires further study." (PMID 27556459, 2016). "ILF2 plays an oncogenic role in the development of malignant tumors by promoting cell proliferation, inhibiting apoptosis, and contributing to tumorigenesis." (PMID 39735599, 2024). "By examining the existing literature, we seek to understand how ILF2 contributes to cancer development and explore its potential as a prognostic marker and therapeutic target." (PMID 39735599, 2024). "Accumulating evidence indicates that ILF2 expression is significantly upregulated in various malignant tumors, including cervical, breast, pancreatic, lung, liver, and esophageal cancers." (PMID 39735599, 2024). "The overexpression of ILF2 in various malignant tumors highlights its potential as a biomarker for early diagnosis and as a target for therapeutic intervention." (PMID 39735599, 2024). "This section explores the multifaceted role of ILF2 in malignant tumors, focusing on its expression patterns, oncogenic activities, and its influence on cell proliferation, survival, cell cycle progression, migration, invasion, and angiogenesis." (PMID 39735599, 2024). "ILF2 gene amplification and overexpression in different human cancers promote cellular processes such as cell growth, programmed cell death, and invasion." (PMID 38622522, 2024). "ILF2 expression is significantly upregulated in various malignant tumors compared to normal tissues." (PMID 39735599, 2024). "Analysis of the Biogrid database revealed that ILF2-interacting proteins are mostly enriched in the DDR signaling pathway, which further supports that the involvement of H19 and ILF2 in the DNA damage response of cancer cells." (PMID 37298108, 2023). "It is documented that upregulation of ILF2 facilitates the initiation of cancers by regulating cell cycle processes." (PMID 35333683, 2022). "It was found that 13 of 28 ESCC patients exhibited high ILF2 expression in ESCC tissues compared to the paired para-cancer tissues." (PMID 34568427, 2021). "To uncover the alterations in metabolic pathways specifically associated with ILF2 protein levels, we analyzed the metabolic differences between the ESCC tissues and para-cancer tissues of patients in each group." (PMID 34568427, 2021). "In contrast, ILF2 showed higher expression levels in the higher-TMB subtype of 13 cancer types, while showed higher expression levels in the lower-TMB subtype of 1 cancer type." (PMID 30634925, 2019). "As expected, ILF2 overexpression significantly decreased apoptosis in cancer cells infected with recombinant ILF2 lentivirus compared with the control group." (PMID 27556459, 2016). "As expected, a rapid growth was observed in cancer cells inoculated with a lentiviral vector coding Flag-ILF2 (Lenti-ILF2) compared with the control cells." (PMID 27556459, 2016). "Among the 16 candidate cancer genes that encoded transcription factors, 13 were known to be tumorigenic and three were novel: CDK1, SNRPF, and ILF2." (PMID 23799036, 2013). "However, the precise mechanisms by which ILF2 contributes to tumorigenesis and cancer progression remain incompletely understood." (PMID 39735599, 2024). "Recent studies have brought attention to the role of ILF2 in cancer biology." (PMID 39735599, 2024).
cancer (continued). "This article reviews the role of ILF2 in malignant tumors and its related mechanisms." (PMID 39735599, 2024). "Given the critical role of ILF2 in various cellular processes and its upregulation in multiple cancers, a thorough review of its biological functions, expression patterns, and regulatory mechanisms in malignant tumors is warranted." (PMID 39735599, 2024). "However, few studies have examined the molecular mechanisms and signaling pathways of ILF2 in related tumors, and little is known clinically about the mechanism of ILF2 in malignant tumors." (PMID 39735599, 2024). "Moreover, analysis of the UCSC Xena database showed that ILF2 levels were enhanced in the primary cancer compared with paired adjacent normal tissues." (PMID 37298108, 2023). "Likewise, increased expression of NUSAP1 and ILF2 are correlated with higher Gleason scores of cancer, the most important clinical predictor of recurrence." (PMID 37047232, 2023). "Importantly, high expression of both ILF2 and SHMT2 was discovered to be closely associated with cancer metastasis." (PMID 35333683, 2022). "ILF3 and ILF2 are overexpressed in several cancer types and contribute to tumorigenesis." (PMID 36012592, 2022). "According to the expression levels of ILF2 in ESCC tissues, the 28 patients were divided into two groups: the patients with a higher expression of ILF2 in cancer tissues than the para-cancer tissues were grouped together (n = 13, group II) and others were another group (n = 15, group I)." (PMID 34568427, 2021). "There are increasing evidences suggesting that ILF2 is highly expressed in various types of cancer." (PMID 30881868, 2019). "As far as we know, high expression of ILF2 has been reported in several malignant tumors." (PMID 28831206, 2017). "Additionally, monitoring ILF2 levels could enhance the early detection of cancers, allowing for timely and effective treatment." (PMID 39735599, 2024). "To better understand the mechanisms underlying the association of NUSAP1 overexpression and cancer aggressiveness, we used AP–MS to identify novel interactions between NUSAP1 and several proteins with described functions in R-loop biology and DDR, including DHX9, ILF2, HNRPC, FUS, and RBMX." (PMID 37047232, 2023). "Overexpression of RUVBL1, RUVBL2, ILF2, ILF3, and HNRNPM are observed in various cancers with their progression (RUVBL1 and RUVBL222,46, ILF2 and ILF347–49, HNRNPM50,51)." (PMID 38225262, 2024). "Therefore, ILF2 may be a potential therapeutic target in HPV-related cancers." (PMID 39735599, 2024). "Therefore, ILF2 may serve as a prognostic biomarker in various cancers." (PMID 39735599, 2024). "Kaplan–Meier analysis demonstrated that cancers with high NUSAP1 and ILF2 mRNA levels had a significantly worse disease-free survival rate." (PMID 37047232, 2023). "ILF3/ILF2 acts as a trans-regulator of RNA editing by interacting with adenosine deaminase RNA specific proteins (DAR1 and ADAR2, providing a link to cancer and epithelial-to-mesenchymal transition)." (PMID 36012592, 2022). "We found that AS-tDR-007333 precipitated with several cancer-related RNA-binding proteins, including HSPB1, DHX9, ACTB, YBX3, and ILF2." (PMID 35526007, 2022). "Those events occurred on pre-mRNA of 56 genes including well-known cancer-related genes PTPRC, IKBKB and HRAS, and genes coding for transcription factors ILF2, ATF2 and EYA3." (PMID 34543356, 2021). "This indicates that ILF2 could be targeted to disrupt HPV oncogene expression, offering a therapeutic strategy against HPV-related cancers." (PMID 39735599, 2024). "In particular, upregulation of ILF2 and YBX1 has been observed in a growing number of cancers." (PMID 36717549, 2023). "Overexpression of NUSAP1 and ILF2 are both upregulated in cancer compared to non-cancerous prostate tissues and both correlate with an increased risk of recurrence after surgery." (PMID 37047232, 2023).
cancer (continued). "Differential expression of ILF2 has previously been observed in some cancers, but the ILF2 function is not clear." (PMID 34709752, 2021). "We propose that increased expression of NUSAP1 and ILF2 drive progression, at least in part through their effects on R-loops and DNA damage; however, it is possible that this is not the major pathway through which these proteins increase cancer aggressiveness." (PMID 37047232, 2023). "Interleukin enhancer-binding factor 3 (ILF3) and ILF2 (also named NF45) were originally discovered as positive regulators of IL2 transcription as part of the NFAT-AP1-NF-kB enhanceosome in activated T-cells and have roles in cancer, autoimmune and inflammatory conditions, and psychiatric disorders." (PMID 36012592, 2022). "In order to explore the regulatory mechanisms that ILF2 and ILF3 may participate in the metabolic disorders of ESCC tissues, we examined the expressed levels of these two proteins in ESCC tissues and paired para-cancer tissues." (PMID 34568427, 2021).
infection (10 papers, 2012 to 2024). The state of being infected such as from the introduction of a foreign agent such as serum, vaccine, antigenic substance or organism. "In contrast, the expression of ILF2 in immune organs, including the BF and spleen, was highly higher compared with that in other tissues during the whole infection process." (PMID 38532469, 2024). "Other proteins with increasing abundance over the course of infection common in both species at d84 vs. d0 (foxes) or d75 vs. d-7 (dogs) were, among others, fibulin 2, interleukin enhancer-binding factor 2, prosaposin, and phosphoglycerate mutase." (PMID 34832667, 2021). "Other significantly and highly increased proteins as of d85 (compared to before infection) were chitinase-3-like protein 1 (A0A3Q7T9N6), pulmonary surfactant-associated protein B (A0A3Q7S3W4), and interleukin enhancer-binding factor 2 (A0A3Q7SCP6; A0A3Q7TCE1)." (PMID 34832667, 2021). "As expected, JEV replication was significantly inhibited at different time points post-infection in 293T cells overexpressing ILF2, determined by Western blot, qRT-PCR, and PFU assays." (PMID 31212927, 2019). "The protein level of ILF2 significantly decreased at 24 h and 36 h post-infection with JEV, which was correlated with the expression of JEV NS3." (PMID 31212927, 2019). "We focused on the role of ILF2 in the infection of JEV in this study." (PMID 31212927, 2019). "For example, ILF2 KD resulted in ~50% cell viability at the end of infection." (PMID 30572664, 2018). "Over-expression of ILF2 resulted in a significantly decrease of virus titers in PRRSV-infected MARC-145 cells at 24 h (p < 0.01), 36 h (p < 0.01), 48 h (p < 0.05) post-infection, suggesting that the over-expression of ILF2 impacts the replication efficiency of PRRSV." (PMID 28693575, 2017). "There was a 5.99-fold, 9.52-fold and 5.27-fold increase of the virus yields in the SiILF2-transfected cells at 24 h (p < 0.01), 36 h (p < 0.001), 48 h (p < 0.05) post-infection, respectively, suggesting that the knockdown of ILF2 favors the replication of PRRSV in MARC-145 cells." (PMID 28693575, 2017). "Interleukin enhancer binding factor 2 (ILF2), a known transcriptional regulator for T-cell-mediated immune defense against biotic stress caused by infection, is up-regulated and hence might be involved in physiological process of euryhalinity." (PMID 22619594, 2012). "In addition, the liver showed the lowest ILF2 expression levels throughout the infection process." (PMID 38532469, 2024). "Among the 14 hits, depletion of ILF2, ILF3, heterogeneous nuclear ribonucleoprotein L (HNRNPL), and STAU1 significantly decreased EBOV-eGFP infection for each siRNA used." (PMID 30301857, 2018). "Moreover, liver tissue, which had the lowest expression of ILF2 at all test time points, showed the highest viral load throughout the infection process, suggesting that DHAV-1 may replicate more effectively in organs with lower ILF2 expression." (PMID 38532469, 2024).
metabolic disease (2 papers, 2021 to 2024). A congenital disorder (due to inherited enzyme abnormality) or acquired (due to failure of a metabolically important organ) disorder resulting from an abnormal metabolic process. "The formation of a complex between ILF2 and S6K protein influences insulin levels and consequently contributes to the progression of metabolic diseases." (PMID 39553470, 2024).
ILF2 also shares sentences with these, for which no sentence is quoted: non-small cell lung carcinoma (7 papers); esophageal squamous cell carcinoma (4); nasopharyngeal carcinoma (3); leukemia (2); Obesity (2); oral squamous cell carcinoma (2); age (1); bacterial infection (1); bladder cancer (1); dengue (1); endodermal sinus tumors (1); heart diseases (1); hyperglycaemia (1); lymphoma (1); malignant glioma (1); meningitis (1); myocarditis (1); psychiatric disorder (1); renal cell carcinoma (1); respiratory failure (1); systemic sclerosis (1); type 2 diabetes (1).